ENSG00000278217
Gene: Miscellaneous RNA gene on chromosome 11 (65,502,914 to 65,503,008, forward strand). Ensembl gene ENSG00000278217.
Gene Ontology:
Biological process: positive regulation of cell motility